HERC2P8 (HERC2 pseudogene 8)
Gene: Transcribed unprocessed pseudogene on chromosome 16 (33,095,029 to 33,128,086, reverse strand). Ensembl gene ENSG00000261599.
Diseases named in the same sentence as HERC2P8 in open-access papers:
HERC2P8 is named in the same sentence as 1 disease in open-access papers, as found by Europe PMC text mining. Sharing a sentence is not in itself a finding about the gene and the disease. The quoted sentences say what the papers report.
tumor (1 paper, 2026). "HERC2P8 is pseudogene with no know biological function, while IFITM3 is a gene that has been shown to modulate the tumor microenvironment by promoting T cell infiltration, which is essential for antitumor immunity." (PMID 41541690, 2026).